SH2D7 (SH2 domain containing 7)
Synonyms: LOC646892
Tractability: No criterion of Open Targets' tractability assessment is met for any kind of drug.
Gene: Protein-coding gene on chromosome 15 (78,077,808 to 78,104,370, forward strand). Ensembl gene ENSG00000183476.
Subcellular location (Human Protein Atlas): Nucleoli; Cytosol; Nucleoplasm
Gene Ontology:
Molecular function: protein-macromolecule adaptor activity
Cellular component: cytoplasm
Genetic constraint (gnomAD): Loss-of-function variants: 33 observed, 41.18 expected, observed/expected ratio (o/e) 0.8, 90% interval 0.61 to 1.07. The upper end of that interval is the gene's LOEUF score, 1.07, which puts it in group 4 of 6, group 1 being the genes least tolerant of losing a copy. Missense variants: 559 observed, 561.96 expected, observed/expected ratio (o/e) 0.99, 90% interval 0.93 to 1.07. Synonymous variants: 195 observed, 225.29 expected, observed/expected ratio (o/e) 0.87, 90% interval 0.77 to 0.98.
Homologues: Orthologues: chimpanzee SH2D7 (98% identical), macaque SH2D7 (93% identical), pig SH2D7 (76% identical), mouse Sh2d7 (67% identical), rat Sh2d7 (66% identical), dog SH2D7 (62% identical), zebrafish sh2d7 (21% identical), Caenorhabditis elegans F13B12.6 (11% identical). Paralogues in human: SH2D2A (17% identical), HSH2D (15% identical), SH2D4A (12% identical), SH2D4B (11% identical).